AVEN (apoptosis and caspase activation inhibitor)
Description:
Protects against apoptosis mediated by Apaf-1.
Synonyms: PDCD12
Tractability: Antibody: UniProt places it where antibodies can reach, with medium confidence; the Human Protein Atlas places it where antibodies can reach. PROTAC: ubiquitination databases record sites on it; its protein half-life has been measured.
Gene: Protein-coding gene on chromosome 15 (33,858,782 to 34,075,155, reverse strand). Ensembl gene ENSG00000169857.
Subcellular location: Endomembrane system
Subcellular location (Human Protein Atlas): Actin filaments; Plasma membrane; Centrosome
Pathways (Reactome):
Programmed Cell Death: Formation of apoptosome; Regulation of the apoptosome activity
Gene Ontology:
Molecular function: protein binding
Biological process: negative regulation of apoptotic process; negative regulation of G2/M transition of mitotic cell cycle
Cellular component: membrane; cytosol; endomembrane system
Genetic constraint (gnomAD): Loss-of-function variants: 28 observed, 32.75 expected, observed/expected ratio (o/e) 0.85, 90% interval 0.63 to 1.17. The synonymous counts are far from expectation, so gnomAD's model fits this gene poorly and the ratio says little. Missense variants: 514 observed, 354.53 expected, observed/expected ratio (o/e) 1.45, 90% interval 1.35 to 1.56. Synonymous variants: 171 observed, 136.25 expected, observed/expected ratio (o/e) 1.25, 90% interval 1.11 to 1.42.
Homologues: Orthologues: chimpanzee AVEN (96% identical), macaque AVEN (93% identical), pig AVEN (73% identical), mouse Aven (68% identical), guinea pig AVEN (58% identical), rat Aven (40% identical), tropical clawed frog aven (35% identical), zebrafish aven (33% identical).
Diseases named in the same sentence as AVEN in open-access papers:
AVEN is named in the same sentence as 14 diseases in open-access papers, as found by Europe PMC text mining. Sharing a sentence is not in itself a finding about the gene and the disease. The quoted sentences say what the papers report.
cervical squamous cell carcinoma (1 paper, 2023). A squamous cell carcinoma arising from the cervical epithelium. "On the other hand, a slight downregulation of AVEN was observed in two types of cancer, Cholangiocarcinoma (CHOL), and Cervical squamous cell carcinoma (CESC)." (PMID 37908231, 2023).
colon adenoma (1 paper, 2023). An adenoma that arises from the colon. "AVEN was highly expressed in six types of cancer compared to normal tissue: colon adenoma (COAD), Kidney renal clear cell carcinoma (KIRC), Kidney renal papillary cell carcinoma (KIRP), Lung adenocarcinoma (LUAD), Lung squamous cell carcinoma (LUSC), and Thyroid carcinoma (THCA)." (PMID 37908231, 2023).
leukemia (1 paper, 2021). A malignant (clonal) hematologic disorder, involving hematopoietic stem cells and characterized by the presence of primitive or atypical myeloid or lymphoid cells in the bone marrow and the blood. "DHX36 has been implicated in leukemia through interaction with apoptosis and caspase activation inhibitor, AVEN, to increase translation of leukemogenic transcriptional regulators MLL1 and MLL4, and subsequent proliferation of leukemic cells." (PMID 33544756, 2021).
psoriasis (1 paper, 2015). An autoimmune condition characterized by red, well-delineated plaques with silvery scales that are usually on the extensor surfaces and scalp. "Similarly, we identified DEG-encoded uDBPs that interact with PREs, whose function in psoriasis is presently unknown (e.g., AVEN, RBM8A, GPAM, WISP2)." (PMID 25883770, 2015). "This highlighted SNP-PRE pairs involving PREs recognized by TFs or uDBPs with increased expression in psoriasis lesions (i.e., AVEN, RBM8A and FOXM1)." (PMID 25883770, 2015). "Several TFs/uDBPs additionally showed altered expression in blood from psoriasis patients (increased: JUNB, STAT3, DTL, CAT; decreased: CUX2, ZNF559, AVEN, RUVBL1, RAN)." (PMID 25883770, 2015). "Through in silico screening of known DNA binding sites, our findings highlight proteins not yet well studied in psoriasis, including TFs (FOXM1, EHF, SOX5) and uDBPs (AVEN, RBM8A, GPAM, WISP2)." (PMID 25883770, 2015).
schizophrenia (1 paper, 2023). A major psychotic disorder characterized by abnormalities in the perception or expression of reality. "The p.Val384Met variant was also previously identified within a pedigree of familial schizophrenia that co-segregated with a variant in the AVEN gene, drawing into question the causality of this variant." (PMID 37841849, 2023).
tumor (3 papers, 2013 to 2023). "Specifically, AVEN expression was positively correlated with the size and/or extent of the main tumor, suggesting the oncogenic role of AVEN." (PMID 37908231, 2023). "FOXD1 (forkhead box protein 1) has a role in tumor formation, while AVEN (apoptosis, caspase activation inhibitor) has an established role in apoptosis regulation." (PMID 23445407, 2013). "Given our interest in the oncogenic role of AVEN, we performed GEPIA analysis to determine the overall survival in the six tumor types with elevated AVEN mRNA expression: COAD, KIRC, KIRP, LUAD, LUSC and THCA." (PMID 37908231, 2023). "Further comprehensive analysis based on TCGA data indicated that the expression level of 3 genes (AVEN, DAZAP2, DNAJB1) were significantly higher in GC tumor tissues than in normal tissues." (PMID 36465351, 2022).
cancer (2 papers, 2019 to 2023). A tumor composed of atypical neoplastic, often pleomorphic cells that invade other tissues. "To analyze the role of AVEN systematically, we examined AVEN mRNA in 33 cancer types and found high AVEN expression in COAD, KIRC, KIRP, LUAD, LUSC and THCA compared to normal tissue, but interestingly high AVEN expression was associated with poor survival only in LUAD." (PMID 37908231, 2023). "Hence, we propose that AVEN overexpression in cancer cells may result from the interplay of miRNA, transcription factor, and epigenetic modifications." (PMID 37908231, 2023). "Although it is unclear which factor regulates AVEN expression in the cancer cells in the absence of genomic amplification, previous studies have suggested potential regulatory mechanism." (PMID 37908231, 2023).
infection (1 paper, 2019). The state of being infected such as from the introduction of a foreign agent such as serum, vaccine, antigenic substance or organism. "Compared to C. albicans SC5314 infection, EGFR triggers two proteins BPHL and AVEN." (PMID 30769958, 2019). "Moreover, according to the experimental data, gene expressions of AVEN and TNFAIP8L1 under the infection of C. albicans SC5314 are lower than C. albicans WO-1." (PMID 30769958, 2019).
AVEN also shares sentences with these, for which no sentence is quoted: breast carcinoma (1 paper); cholangiocarcinoma (1); lung adenocarcinoma (1); Lung squamous cell carcinoma (1); osteosarcoma (1); Thyroid carcinoma (1).